C2CD4B (C2 calcium dependent domain containing 4B)
Description:
May be involved in inflammatory process. May regulate cell architecture and adhesion.
Synonyms: FAM148B; NLF2
Tractability: No criterion of Open Targets' tractability assessment is met for any kind of drug.
Gene: Protein-coding gene on chromosome 15 (62,163,535 to 62,165,719, reverse strand). Ensembl gene ENSG00000205502.
Subcellular location: Nucleus
Gene Ontology:
Biological process: positive regulation of acute inflammatory response; regulation of cell adhesion; regulation of vascular permeability involved in acute inflammatory response
Cellular component: nucleus
Genetic constraint (gnomAD): Missense variants: 476 observed, 264.16 expected, observed/expected ratio (o/e) 1.8, 90% interval 1.67 to 1.93. Synonymous variants: 251 observed, 129.42 expected, observed/expected ratio (o/e) 1.94, 90% interval 1.73 to 1.99.
Homologues: Orthologues: chimpanzee C2CD4B (97% identical), macaque C2CD4B (88% identical). Paralogues in human: C2CD4A (81% identical), C2CD4C (34% identical), C2CD4D (29% identical), SYTL1 (16% identical), SYT11 (15% identical), SYT3 (15% identical), SYTL5 (15% identical), RPH3A (15% identical), SYT15 (15% identical), SYT15B (15% identical), SYT4 (14% identical), SYT9 (14% identical), and 19 more.
Diseases named in the same sentence as C2CD4B in open-access papers:
C2CD4B is named in the same sentence as 8 diseases in open-access papers, as found by Europe PMC text mining. Sharing a sentence is not in itself a finding about the gene and the disease. The quoted sentences say what the papers report.
diabetes (5 papers, 2012 to 2024). "C2cd4b, a gene implicated in diabetes and proinsulin to insulin conversion via a genome-wide association study, was differentially expressed but the cellular function and relevance of C2cd4b to diabetes has yet to be validated." (PMID 29543849, 2018). "Dietary habits influence the association of six genes (C2CD4B, CDKN2B, GIPR, HHEX, SLC2A2, and SLC30A8) forming the third cluster with diabetes, adipogenesis, and cardiovascular risk." (PMID 36982283, 2023). "C2cd4a and C2cd4b were both upregulated in pancreatic islets of high-fat-diet--fed DBA2J mouse model of diabetes following 30 and 90 days of the diet vs RC-fed mice." (PMID 33492421, 2021). "Thus, targeting C2CD4B opens a new therapeutic avenue for preventing vascular complications in patients with diabetes mellitus." (PMID 38247525, 2024). "While genome-wide studies have identified an association between type 2 diabetes mellitus (T2DM) and increased expression of a C2 calcium-dependent domain containing 4B (C2CD4B), no study has yet explored the possible direct effect of C2CD4B on vascular function." (PMID 38247525, 2024).
type 2 diabetes (5 papers, 2010 to 2025). "Genome-wide association studies revealed that single nucleotide polymorphisms (SNPs) in close proximity to the VPS13C, C2CD4A, and C2CD4B genes on chromosome 15q contribute to an increased risk of type 2 diabetes." (PMID 38247525, 2024). "The increased expression of C2cd4b has been associated with an increased risk of type 2 diabetes and increased expression of C2cd4b in old mice pancreatic cell types may suggest the increased risk of type 2 diabetes for these mice." (PMID 33847263, 2021). "Similarly, transcripts of candidate genes for type 2 diabetes (Blk, C2cd4a, C2cd4b, Cdkn2a, Hnf1a, Mtnr1b, Pou5f1, Slc30a8) and type 1 diabetes (Cd69, Il2, IL27) were not expressed in the brain." (PMID 39920851, 2025).
endothelial dysfunction (1 paper, 2024). In vascular diseases, endothelial dysfunction is a systemic pathological state of the endothelium (the inner lining of blood vessels) and can be broadly defined as an imbalance between vasodilating and vasoconstricting substances produced by (or acting on) the endothelium. "Mechanistically, via activation of the PI3K/Akt/PKCα–pathway, C2CD4B promotes oxidative stress–dependent endothelial dysfunction, driving eNOS uncoupling and NADPH oxidase dysregulation." (PMID 38247525, 2024). "More importantly, the knockdown of C2CD4B protects against high glucose–induced oxidative stress and endothelial dysfunction." (PMID 38247525, 2024).
Hyperglycemia (1 paper, 2024). An increased concentration of glucose in the blood. "Here we present, for the first time, evidence demonstrating that hyperglycemia increased mRNA expression of the diabetic–associated protein C2CD4B." (PMID 38247525, 2024).
cancer (1 paper, 2025). A tumor composed of atypical neoplastic, often pleomorphic cells that invade other tissues. "Additionally, C2cd4b, a marker of acute inflammation, and Dlk1, a driver of Wnt signaling, lung repair and stemness, and cancer stemness, were downregulated." (PMID 40356899, 2025).
C2CD4B also shares sentences with these, for which no sentence is quoted: Osteochondrosis (1 paper); posterior uveitis (1); type 1 diabetes (1).